UBE2G2 (ubiquitin conjugating enzyme E2 G2)
Description:
Accepts ubiquitin from the E1 complex and catalyzes its covalent attachment to other proteins. In vitro catalyzes 'Lys-48'-linked polyubiquitination. Involved in endoplasmic reticulum-associated degradation (ERAD). Required for sterol-induced ubiquitination of 3-hydroxy-3-methylglutaryl coenzyme A reductase and its subsequent proteasomal degradation.
Synonyms: UBC7
Tractability: PROTAC: ubiquitination databases record sites on it; its protein half-life has been measured.
Target class: Enzyme; Transferase
Gene: Protein-coding gene on chromosome 21 (44,768,580 to 44,801,826, reverse strand). Ensembl gene ENSG00000184787.
Subcellular location: Endoplasmic reticulum; Lipid droplet
Pathways (Reactome):
Immune System: Antigen processing: Ubiquitination & Proteasome degradation
Metabolism of proteins: Synthesis of active ubiquitin: roles of E1 and E2 enzymes
Gene Ontology:
Molecular function: protein binding; ubiquitin conjugating enzyme activity; ubiquitin-protein transferase activity; identical protein binding
Biological process: cellular response to interferon-beta; ERAD pathway; negative regulation of retrograde protein transport, ER to cytosol; protein K48-linked ubiquitination; protein polyubiquitination; ubiquitin-dependent protein catabolic process; protein modification by small protein conjugation; protein ubiquitination
Cellular component: cytosol; endoplasmic reticulum; lipid droplet
Genetic constraint (gnomAD): Loss-of-function variants: 10 observed, 20.67 expected, observed/expected ratio (o/e) 0.48, 90% interval 0.3 to 0.82. The upper end of that interval is the gene's LOEUF score, 0.82, which puts it in group 3 of 6, group 1 being the genes least tolerant of losing a copy. Missense variants: 150 observed, 207.15 expected, observed/expected ratio (o/e) 0.72, 90% interval 0.63 to 0.83. Synonymous variants: 86 observed, 74.86 expected, observed/expected ratio (o/e) 1.15, 90% interval 0.96 to 1.38.
Homologues: Orthologues: chimpanzee UBE2G2 (100% identical), mouse Ube2g2 (100% identical), guinea pig UBE2G2 (99% identical), rat Ube2g2 (99% identical), tropical clawed frog ube2g2 (96% identical), zebrafish ube2g2 (94% identical), pig UBE2G2 (92% identical), Drosophila melanogaster Ubc7 (82% identical), Caenorhabditis elegans ubc-14 (77% identical), dog UBE2G2 (76% identical), macaque UBE2G2 (75% identical), rabbit UBE2G2 (74% identical). Paralogues in human: UBE2G1 (52% identical), UBE2R2 (48% identical), CDC34 (48% identical), UBE2A (30% identical), UBE2B (30% identical), UBE2I (29% identical), UBE2N (27% identical), UBE2C (27% identical), UBE2T (25% identical), UBE2W (25% identical), UBE2NL (25% identical), UBE2J1 (24% identical), and 12 more.
Diseases named in the same sentence as UBE2G2 in open-access papers:
UBE2G2 is named in the same sentence as 14 diseases in open-access papers, as found by Europe PMC text mining. Sharing a sentence is not in itself a finding about the gene and the disease. The quoted sentences say what the papers report.
glioma (1 paper, 2022). A benign or malignant brain and spinal cord tumor that arises from glial cells (astrocytes, oligodendrocytes, ependymal cells). "USP7, UBE2G2, and BTRC were associated with better prognosis of glioma(HR<1, P<0.001)." (PMID 35774799, 2022).
Hypoglycemia (1 paper, 2021). A decreased concentration of glucose in the blood. "Notably UBE2N, UBE2L3, and STIP1 all significantly go down in controls but not at all in T2D in response to hypoglycemia, whilst the protein that is linked within the system, UBE2G2, was unaffected by hypoglycemia, though significantly lower than levels seen in T2D at all time points." (PMID 34426634, 2021). "Why the levels of UBE2N, UBE2L3 and STIP1 should fall in the control subjects in response to hypoglycemia, whilst UBE2G2 showed no apparent change in level, is unclear, and whether the loss of regulation of these specific and tightly controlled proteins would lead to a detrimental effect is unknown." (PMID 34426634, 2021).
lentivirus infection (1 paper, 2025). Virus diseases caused by the Lentivirus genus. "To investigate whether UBE2G2 regulates the STING-mediated innate immune response in mouse cell lines, we knocked down Ube2g2 in L292 cells using lentivirus infection with shRNA." (PMID 40237449, 2025).
leukemia (1 paper, 2016). A malignant (clonal) hematologic disorder, involving hematopoietic stem cells and characterized by the presence of primitive or atypical myeloid or lymphoid cells in the bone marrow and the blood. "UBE2G2 is a mutant gene in human leukemia and SIK3 has been recently identified as a tumor antigen associated with ovarian cancer tumorigenesis." (PMID 27494850, 2016).
neuroblastoma (1 paper, 2021). Neuroblastoma (NB) is the most common solid, extracranial childhood tumor. "A similar loss of UBE2G2 and rescue by GFP-G2BR overexpression was observed in HEK293 AUP1 KO cells, and a dependency of E2 stability on AUP1 was also observed in M17, a neuroblastoma cell line." (PMID 34879065, 2021).
Obesity (1 paper, 2021). Accumulation of substantial excess body fat. "This raises the interesting possibility that accumulation of lipid droplets in cells, such as observed in obesity, could affect ERAD by altering the availability or level of UBE2G2." (PMID 34879065, 2021).
osteonecrosis (1 paper, 2021). A none disease characterized by death of bone tissue due to a lack of blood supply. "In the Steroid-induced osteonecrosis of the femoral head-bone marrow mesenchymal stem cells, five circRNA targeted mRNAs including CLASP1, ENOX2, SYK, UBE2G2, and WNT5B were up-regulated by circRNA42." (PMID 34753940, 2021).
virus infection (1 paper, 2023). "While in both the wild-type and Ube2g2-deficient cells, virus infection triggered increased Xbp1 splicing, the basal levels of spliced Xbp1 were substantially higher in Ube2g2−/− cells compared to that of wild-type." (PMID 37164963, 2023). "Interestingly, in both Sec62 and Chmp4-depleted cells, defective virus production upon Ube2g2-deficiency was rescued to wild-type levels, in support of the hypothesis that Ube2g2 inhibits this pathway during virus infection." (PMID 37164963, 2023). "To study the functional impact of Ube2g2 on virus infection, we generated Ube2g2−/− HeLa cells using CRISPR/Cas9 gene editing." (PMID 37164963, 2023).
Zika virus infection (1 paper, 2023). "To further investigate if the catalytic activity of Ube2g2 was essential during Zika virus infection, we generated a cell line stably expressing a catalytically inactive form of Ube2g2 using site-directed mutagenesis." (PMID 37164963, 2023).
tumor (6 papers, 2016 to 2025). "Similarly, the enzyme UBE2G2 is associated with protein degradation pathways, affecting tumor growth and therapy resistance in androgen-independent prostate cancer." (PMID 40491606, 2025). "Further, we detected several genes that were both mutated and differentially spliced in the same cell types, such as HMGN3 and UBE2G2 in tumor cells, CD74 and IFI30 in myeloid cells, and RPS2 in endothelial cells indicating their important roles in tumorigenicity." (PMID 37433798, 2023). "In TCGA database, the expressions of four potential tumor suppressor genes (UBL3, TRIM22, UBE2G2, and MARCH1) were significantly downregulated in tumor samples compared to that in normal lung tissues." (PMID 32296577, 2020).
infection (3 papers, 2017 to 2025). The state of being infected such as from the introduction of a foreign agent such as serum, vaccine, antigenic substance or organism. "The abundance of FAM134B however was found to decrease over the time course of infection in Ube2g2-deficient cells, most likely due to FAM134B-independent ER-phagy." (PMID 37164963, 2023). "In both wild-type and Ube2g2-deficient cells, infection was accompanied by XBP1 splicing." (PMID 37164963, 2023). "Our data therefore indicate that Ube2g2 deficiency resulted in stabilisation of stress response chaperones along with increased expression of Sec62, which consequently triggers Sec62-dependent ER-phagy during infection." (PMID 37164963, 2023). "As anticipated, Ube2g2 interacted with Aup1 in both mock and virus-infected samples during the course of infection." (PMID 37164963, 2023). "Defective lipophagy was not due to loss of Aup1, since its expression levels in Ube2g2-deficient cells remained unaffected even at late timepoints in infections." (PMID 37164963, 2023). "These analyses showed that depletion of DOHH, PRKRA, SEL1L, UBE2G2, and ZFP36L2 consistently decreased DENV-2 viral protein and RNA levels during infection of Huh7.5.1 cells (respectively)." (PMID 41372121, 2025). "Interestingly, while synthesis of the structural proteins (E, prM) was only mildly slower in Ube2g2-deficient cells, particularly at 24 h post infection, synthesis of non-structural proteins was followed by their rapid degradation over time in the rUbe2g2−/− and rUbe2g2C89K cells." (PMID 37164963, 2023).
UBE2G2 also shares sentences with these, for which no sentence is quoted: dengue (1 paper); ovarian carcinoma (1); trisomy 21 (1).